SLC25A30-AS1 (SLC25A30 antisense RNA 1)
Gene: Long non-coding RNA gene on chromosome 13 (45,418,162 to 45,436,858, forward strand). Ensembl gene ENSG00000251015.
Diseases named in the same sentence as SLC25A30-AS1 in open-access papers:
SLC25A30-AS1 is named in the same sentence as 2 diseases in open-access papers, as found by Europe PMC text mining. Sharing a sentence is not in itself a finding about the gene and the disease. The quoted sentences say what the papers report.
tumours (1 paper, 2023). "SLC25A30AS1 and LINC01063 are only shown to be constituent factors in the tumour prognosis model, but their specific role in tumours has not been studied." (PMID 36844873, 2023).
SLC25A30-AS1 also shares sentences with these, for which no sentence is quoted: liver cancer (1 paper).